AKAP8L (A-kinase anchoring protein 8 like)
Description:
Could play a role in constitutive transport element (CTE)- mediated gene expression by association with DHX9. Increases CTE-dependent nuclear unspliced mRNA export. Proposed to target PRKACA to the nucleus but does not seem to be implicated in the binding of regulatory subunit II of PKA. May be involved in nuclear envelope breakdown and chromatin condensation. May be involved in anchoring nuclear membranes to chromatin in interphase and in releasing membranes from chromating at mitosis. May regulate the initiation phase of DNA replication when associated with TMPO isoform Beta. Required for cell cycle G2/M transition and histone deacetylation during mitosis. In mitotic cells recruits HDAC3 to the vicinity of chromatin leading to deacetylation and subsequent phosphorylation at 'Ser-10' of histone H3; in this function seems to act redundantly with AKAP8. May be involved in regulation of pre-mRNA splicing. (Microbial infection) In case of EBV infection, may target PRKACA to EBNA-LP-containing nuclear sites to modulate transcription from specific promoters. (Microbial infection) Can synergize with DHX9 to activate the CTE-mediated gene expression of type D retroviruses. (Microbial infection) In case of HIV-1 infection, involved in the DHX9-promoted annealing of host tRNA(Lys3) to viral genomic RNA as a primer in reverse transcription; in vitro negatively regulates DHX9 annealing activity.
Synonyms: HAP95; HA95; NAKAP; NAKAP95
Tractability: PROTAC: ubiquitination databases record sites on it; its protein half-life has been measured.
Gene: Protein-coding gene on chromosome 19 (15,380,050 to 15,419,141, reverse strand). Ensembl gene ENSG00000011243.
Subcellular location: Nucleus; Nucleus matrix; Nucleus speckle; Nucleus, PML body; Cytoplasm
Subcellular location (Human Protein Atlas): Nuclear speckles
Pathways (Reactome):
Gene expression (Transcription): Formation of WDR5-containing histone-modifying complexes
Gene Ontology:
Molecular function: histone deacetylase binding; lamin binding; protein binding; RNA binding; DEAD/H-box RNA helicase binding; protein kinase A regulatory subunit binding; DNA binding
Biological process: cell cycle G2/M phase transition; mitotic chromosome condensation; mRNA processing; nuclear membrane disassembly; positive regulation of transcription by RNA polymerase II; regulation of mRNA export from nucleus
Cellular component: chromatin; cytoplasm; nuclear matrix; nuclear speck; nucleus; ribonucleoprotein complex; nucleoplasm; PML body
Genetic constraint (gnomAD): Loss-of-function variants: 33 observed, 74.59 expected, observed/expected ratio (o/e) 0.44, 90% interval 0.33 to 0.59. The upper end of that interval is the gene's LOEUF score, 0.59, which puts it in group 2 of 6, group 1 being the genes least tolerant of losing a copy. Missense variants: 806 observed, 878.19 expected, observed/expected ratio (o/e) 0.92, 90% interval 0.87 to 0.97. Synonymous variants: 342 observed, 335.59 expected, observed/expected ratio (o/e) 1.02, 90% interval 0.93 to 1.12.
Homologues: Orthologues: chimpanzee AKAP8L (99% identical), macaque AKAP8L (98% identical), mouse Akap8l (92% identical), rabbit AKAP8L (92% identical), pig AKAP8L (89% identical), rat Akap8l (88% identical), guinea pig AKAP8L (84% identical), zebrafish akap8l (35% identical), tropical clawed frog akap8l (32% identical). Paralogues in human: AKAP8 (34% identical), ZNF326 (23% identical).
Diseases named in the same sentence as AKAP8L in open-access papers:
AKAP8L is named in the same sentence as 29 diseases in open-access papers, as found by Europe PMC text mining. Sharing a sentence is not in itself a finding about the gene and the disease. The quoted sentences say what the papers report.
breast carcinoma (2 papers, 2021 to 2023). "Previous studies have proved that AKAP8L was linked to the molecular subtypes of breast cancer." (PMID 37683130, 2023). "The gene AKAP8L had the highest closeness centrality in HER2 enriched breast cancer." (PMID 34326402, 2021).
esophageal carcinoma (2 papers, 2022 to 2023). A primary or metastatic malignant neoplasm involving the esophagus. "The mRNA expression of AKAP8L was significantly higher in multiple type of cancer tissues than in the corresponding normal tissues, including esophageal carcinoma (ESCA)." (PMID 35189899, 2022).
esophageal squamous cell carcinoma (2 papers, 2022 to 2023). Esophageal squamous cell carcinoma (ESCC) is a type of esophageal carcinoma (EC) that can affect any part of the esophagus, but is usually located in the upper or middle third. "It has been previously proved that the high AKAP8L expression is associated with poor prognosis in esophageal squamous cell carcinoma, serving as an independent prognostic factor for the disease." (PMID 37683130, 2023). "As demonstrated by studies, AKAP8L stimulates cell proliferation / migration in various cancers, such a sd colon cancer, gastric cancer and esophageal squamous cell carcinoma, and can interact with mTORC1 and promote cell growth." (PMID 37683130, 2023).
gastric cancer (2 papers, 2022 to 2023). A primary or metastatic malignant neoplasm involving the stomach. "The effect of AKAP8L overexpression on Oxa chemotherapy was examined on BGC-823/Oxa gastric cancer xenografts in mice." (PMID 36522343, 2022). "In the present study, forced AKAP8L expression in gastric cancer cells dramatically enhanced SCD1 mRNA level by maintenance SCD1 mRNA stability." (PMID 36522343, 2022). "Overexpression of AKAP8L in gastric cancer cells led to a ~52% increase in spheroid number (>50 μm) compared to that in the control cells." (PMID 36522343, 2022). "Two shRNAs (AKAP8L shRNA-1; AKAP8L shRNA-2) in gastric cancer cells led to a ~47% decrease in spheroid number compared to that in the control cells." (PMID 36522343, 2022). "Ectopic AKAP8L in gastric cancer cells and spheroids elevated the expression of stem cell markers, including Lgr5, CD133, CD44, Oct4, Sox2, as determined by qPCR, Western blot analysis." (PMID 36522343, 2022). "Therefore, our study identifies AKAP8L as a prognostic marker and a therapeutic target for overcoming chemoresistance in gastric cancer." (PMID 36522343, 2022). "Further research on the inhibition of AKAP8L could provide opportunities for AKAP8L-targeted therapies in chemoresistant gastric cancer." (PMID 36522343, 2022). "In summary, our data showed the role of AKAP8L in Oxa-resistant gastric cancer cells." (PMID 36522343, 2022). "In the clinical setting, our data demonstrated that AKAP8L and SCD1 were upregulated in gastric cancer patients resistant to chemotherapy." (PMID 36522343, 2022). "In conclusion, we confirmed that AKAP8L and SCD1 were upregulated in gastric cancer patients resistant to chemotherapy, consistent with the findings obtained from in-vitro cellular experiments." (PMID 36522343, 2022).
viral infection (2 papers, 2020 to 2022). "SARS-CoV-2 Membrane (M) protein interacts with AKAP8L, which assists in viral infection progression through favoring transcription." (PMID 33224264, 2020).
Alzheimer disease (1 paper, 2024). A progressive, neurodegenerative disease characterized by loss of function and death of nerve cells in several areas of the brain leading to loss of cognitive function such as memory and language. "Furthermore, by examining the Alzheimer’s Disease (AD) postmortem database, we noted a consistent upregulation of AKAP8L expression in AD patients." (PMID 39033121, 2024).
anemia (1 paper, 2022). A reduction in the number of red blood cells, the amount of hemoglobin, and/or the volume of packed red blood cells. "Further studies of AKAP8L in the future may help to provide a comprehensive understanding of the underlying mechanisms of nuclear rupture and the diversity of cell stages in different types of anemia." (PMID 35189899, 2022).
autism (1 paper, 2015). Persistent deficits in social interaction and communication and interaction as well as a markedly restricted repertoire of activity and interest as well as repetitive patterns of behavior. "Taken together, findings support the idea that gene dosage at 19p13.12, and AKAP8 and/or AKAP8L in particular, play an important role in modulation of head size and may contribute to autism risk." (PMID 26076356, 2015). "Towards determination of which of AKAP8 and AKAP8L may be involved in the modulation of head size and risk for disease, we analyzed exome sequencing data for 693 autism families (2591 individuals) where head circumference data were available." (PMID 26076356, 2015). "We present here a patient with autism and ID with an inherited duplication at 19p13.12 and discuss the relationship between altered gene dosage at this locus, involving AKAP8 and/or AKAP8L in particular, and each of head size and autism." (PMID 26076356, 2015). "Data support A kinase anchor protein 8 and 8-like (AKAP8 and AKAP8L) as candidate genes involved in regulation of head growth, an interesting finding given previous work implicating the AKAP gene family in autism." (PMID 26076356, 2015).
diabetes (1 paper, 2024). "Prior research has also documented significant increases in AKAP8L levels in the plasma of patients afflicted with diabetic liver disease, underscoring the substantial involvement of AKAP8L in the complications associated with diabetes." (PMID 39033121, 2024).
gastric tumor (1 paper, 2022). "Furthermore, we performed IHC on 76 paraffin-embedded gastric tumor samples, and observed the higher expression of AKAP8L and SCD1 in tumor tissues from resistant patients compared with sensitive patients." (PMID 36522343, 2022).
lymph node metastasis (1 paper, 2022). "Besides, AKAP8L expression was highly expressed in patients with lymph node metastasis detected by ESCC tissue microarray (p = 0.0014)." (PMID 35189899, 2022).
pituitary tumor (1 paper, 2025). A benign or malignant neoplasm affecting the pituitary gland. "In the pituitary tumor cohort (GSE169498), we identified a total of five MRGs (MED27, RARRES2, AKAP8L, RAB5B, and STK39) that are associated with the invasiveness of pituitary tumors." (PMID 40873641, 2025).
renal clear cell carcinoma (1 paper, 2023). "Furthermore, we focused on renal clear cell carcinoma (KIRC), and of explored the correlation of AKAP8L with clinical characteristics, prognosis of distinct patient subsets, co-expression genes and differentially expressed genes (DEG)." (PMID 37683130, 2023).
cancer (4 papers, 2013 to 2023). A tumor composed of atypical neoplastic, often pleomorphic cells that invade other tissues. "To gain a comprehensive understanding of AKAP8L, we explored its expression as well as biological function of AKAP8L across various types of cancer, with a focus on its potential as a marker for early diagnosis and outcome prediction." (PMID 37683130, 2023). "Our findings indicate that AKAP8L expression varied significantly not only across most cancer types, but also across different cancer molecules and immune subtypes." (PMID 37683130, 2023). "Our analysis revealed that AKAP8L was significantly up-regulated in 13 human cancers, but down-regulated in KICH." (PMID 37683130, 2023). "A-kinase anchor-protein 8-like (AKAP8L) is a member of the A kinase anchor-protein (AKAPs) family and is overexpressed in many cancers." (PMID 35189899, 2022). "In this study, we initially analyzed the mRNA expression level of AKAP8L in a pan-cancer sample obtained from the TCGA dataset." (PMID 35189899, 2022). "We first analyzed the gene expression levels of AKAP8L in different human cancer tissues as compared with those in normal tissues based on data obtained from the TCGA database." (PMID 35189899, 2022). "We found that, compared with normal tissues, AKAP8L mRNA levels increased significantly in many cancers, including ESCC." (PMID 35189899, 2022). "UALCAN database was adopted for the assessment of the methylation level of AKAP8L across various types of cancer and found a close relationship between the methylation of AKAP8L promoter and the progression of various tumors, including BLCA, CHOL, KIRP, KIRC, LIHC and LUSC." (PMID 37683130, 2023). "We found that AKAP8L was up-regulated or down-regulated in 14 human cancers, and its expression varied across molecular subtypes of 11 cancer types as well as immune subtypes of 7 cancer types." (PMID 37683130, 2023). "AKAP8L has played the role of oncogene in most malignant tumors and may take part in the initiation and progression of tumors." (PMID 37683130, 2023). "Our research provided a new dimension for a comprehensive understanding of the key role of AKAP8L in tumor progression, and a solid theoretical basis for the discovery of novel targets as well as prognostic markers for cancer treatment, with a particular emphasis on KIRC." (PMID 37683130, 2023). "In addition, the robust ability to accurately predict cancer and its strong correlation with the prognosis of cancer strongly suggest that AKAP8L may be a potential biomarker for cancer diagnosis and prognosis." (PMID 37683130, 2023). "Thus, our study on different cancer molecular subtypes or immune subtypes may provide a suitable entry point for the exploration of the role of AKAP8L." (PMID 37683130, 2023). "As previously reported, AKAP8L may play a part in different cancers." (PMID 37683130, 2023). "AKAP8L, the homolog of the scaffold protein AKAP8, links M protein cluster to E and N members in the PPI network, influencing cancer cell tumorigenesis and metastasis." (PMID 36528612, 2022). "Currently, no study has investigated the significance of AKAP8L in a pan-cancer context." (PMID 37683130, 2023). "However, no study has investigated the expression profile of AKAP8L in human cancer, and the function and clinical significance of AKAP8L in ESCC remain unclear." (PMID 35189899, 2022).
tumor (4 papers, 2022 to 2024). "We next evaluated the association of AKAP8L expression in tumor tissues with the following clinicopathologic parameters: gender, the age of diagnosed, tumor-differentiation grade, T stage, N stage, distant metastasis, and clinical stage." (PMID 35189899, 2022). "IHC analysis revealed that in all 10 pairs of samples, compared to adjacent normal tissue, AKAP8L protein expression was higher in KIRC tumor tissues with statistical significance." (PMID 37683130, 2023). "IHC staining of AKAP8L in a tumor tissue microarray of ESCC patients revealed higher AKAP8L expression in ESCC patients with lymphatic metastasis." (PMID 35189899, 2022). "The results showed that positive staining of AKAP8L was predominately present in the nucleus of tumor cells, which was observed in 93.97% (109/116) of ESCC tissues." (PMID 35189899, 2022). "AKAP8L accelerated tumor growth by approximately 2- to 3-fold compared with the tumors treated with Oxa." (PMID 36522343, 2022). "AKAP8L is involved in many biological processes, but the function of AKAP8L in tumor development is unclear." (PMID 35189899, 2022). "We found that the mRNA level of AKAP8L was higher in tumor tissues than in adjacent tissues in TCGA and GEO dataset." (PMID 35189899, 2022). "AKAP8L expression was higher in ESCC tumor tissues than in normal tissues in both datasets." (PMID 35189899, 2022). "Similarly, AKAP8L was also expressed among most tumor cell lines." (PMID 37683130, 2023). "Therefore, investigating AKAP8L expression profile in tumor tissues and its impact on clinical prognosis may help us understand its functional role." (PMID 35189899, 2022). "Spearman correlation was adopted to investigate the relationship between the expression level of AKAP8L (TPM) and the level of GSEA quantitative immune cell infiltration in tumor microenvironment of KIRC." (PMID 37683130, 2023). "The protein sequence of AKAP8L exhibits a similarity of up to 61% with that of AKAP8, suggesting that AKAP8L and AKAP8 may have similar functions in tumor genesis and metastasis." (PMID 37683130, 2023). "High AKAP8L expression levels significantly correlated with N categories, but not with sex, age, histological differentiation grade, and tumor status or TNM stage of ESCC patients." (PMID 35189899, 2022). "AKAP8L, a member of the A-kinase anchor protein (AKAP) family renowned for its role in localizing protein kinase A (PKA) to distinct subcellular sites, has emerged as a focal point in research exploring its contributions to tumor development and a spectrum of biological functions." (PMID 39033121, 2024).
AKAP8L also shares sentences with these, for which no sentence is quoted: breast invasive carcinoma (1 paper); cholangiocarcinoma (1); Cognitive impairment (1); colon adenocarcinoma (1); colon cancer (1); glioblastoma (1); head and neck squamous cell carcinoma (1); HIV-1 infection (1); Huntington disease (1); lung adenocarcinoma (1); lung squamous cell carcinoma (1); prostate adenocarcinoma (1); stomach adenocarcinoma (1); testicular germ cell tumor (1).